CCN6 (cellular communication network factor 6)
Description:
Plays a role in mitochondrial electron transport and mitochondrial respiration. Through its regulation of the mitochondrial function may play a role in normal postnatal skeletal growth and cartilage homeostasis.
Synonyms: WISP-3; WISP3; LIBC; PPAC; PPD; PPRD
Tractability: Antibody: UniProt places it where antibodies can reach, with high confidence; UniProt predicts a signal peptide or a membrane-spanning region; its Gene Ontology location is reachable by antibodies, with medium confidence. PROTAC: ubiquitination databases record sites on it.
Gene: Protein-coding gene on chromosome 6 (112,054,075 to 112,069,686, forward strand). Ensembl gene ENSG00000112761.
Subcellular location: Secreted; Mitochondrion
Subcellular location (Human Protein Atlas): Mitochondria; Predicted to be secreted
Gene Ontology:
Molecular function: heparin binding; integrin binding
Biological process: negative regulation of angiogenesis; negative regulation of cell population proliferation; regulation of mitochondrial membrane potential; regulation of reactive oxygen species biosynthetic process; cell adhesion; cell-cell signaling; positive regulation of cell differentiation; signal transduction; regulation of developmental process
Cellular component: extracellular region; mitochondrion; non-collagenous component of interstitial matrix; extracellular matrix
Genetic constraint (gnomAD): Loss-of-function variants: 31 observed, 39.65 expected, observed/expected ratio (o/e) 0.78, 90% interval 0.59 to 1.05. The upper end of that interval is the gene's LOEUF score, 1.05, which puts it in group 4 of 6, group 1 being the genes least tolerant of losing a copy. Missense variants: 369 observed, 436.55 expected, observed/expected ratio (o/e) 0.85, 90% interval 0.77 to 0.92. Synonymous variants: 137 observed, 151.13 expected, observed/expected ratio (o/e) 0.91, 90% interval 0.79 to 1.04.
Gene-disease validity (ClinGen):
ClinGen rates the evidence that CCN6 causes each of these diseases.
progressive pseudorheumatoid arthropathy of childhood (autosomal recessive): Definitive. Progressive pseudorheumatoid arthropathy (dysplasia) of childhood (PPAC; PPD) presents as spondyloepiphyseal dysplasia (SED) tarda with progressive arthropathy and is described as a specific autosomal recessive subtype of SED.
Homologues: Orthologues: chimpanzee CCN6 (99% identical), macaque CCN6 (97% identical), rabbit CCN6 (86% identical), pig CCN6 (86% identical), guinea pig CCN6 (81% identical), mouse Ccn6 (78% identical), rat Ccn6 (75% identical), dog CCN6 (62% identical), tropical clawed frog CCN6 (55% identical), zebrafish ccn6 (55% identical). Paralogues in human: CCN4 (42% identical), CCN2 (38% identical), CCN1 (35% identical), CCN3 (34% identical), CCN5 (23% identical).
Diseases named in the same sentence as CCN6 in open-access papers:
CCN6 is named in the same sentence as 68 diseases in open-access papers, as found by Europe PMC text mining. Sharing a sentence is not in itself a finding about the gene and the disease. The quoted sentences say what the papers report.
breast carcinoma (26 papers, 2005 to 2026). "The high frequency of reduction or loss of CCN6 in biologically aggressive breast cancer suggests a potential role in breast cancer initiation and/or progression." (PMID 26933820, 2016). "WISP3/CCN6 expression is linked to the severity of breast cancer and is implicated in regulating the epithelial to mesenchymal transition (EMT)." (PMID 23977121, 2013). "CCN6 maps to chromosome 6q21-22, a locus that displays high rates of loss of heterozygosity in breast cancer." (PMID 16457688, 2005). "CCN6 is a breast cancer tumor suppressor gene that encodes a secreted protein." (PMID 38264570, 2023). "However, frameshift mutations in the Ccn6 gene have been detected in a subset of human metaplastic breast carcinomas." (PMID 37608493, 2023). "Moreover, the downregulation of cellular communication network factor 6 (CCN6) is associated with EMT activation in breast cancer cells as well as with axillary lymph node metastasis in breast cancer." (PMID 31514467, 2019). "It is possible that the loss of CCN6 might lead to increased methylation of the E-cadherin promoter, which has been shown to be correlated with a loss of E-cadherin expression in breast cancer cell lines and primary invasive ductal and lobular carcinomas of the breast." (PMID 16457688, 2005). "Here, we employed photoacoustic chemical imaging (PACI) with a solvatochromic dye-based, potassium-sensitive nanoprobe (SDKNP) to quantitatively visualize extracellular potassium levels in an orthotopic metaplastic breast cancer mouse model, Ccn6-KO." (PMID 40807890, 2025). "In this study, we successfully applied PACI with a K+-sensitive nanoprobe (SDKNP) to noninvasively visualize extracellular K+ levels in vivo in orthotopic Ccn6-KO mataplastic breast carcinomas of varying sizes." (PMID 40807890, 2025). "Mice bearing orthotopic Ccn6-KO metaplastic breast cancer tumors were divided into three groups based on tumor size, as measured along the longest dimension: Group 1 (5 mm, n = 4), Group 2 (10 mm, n = 3), and Group 3 (20 mm, n = 4)." (PMID 40807890, 2025). "CCN6 has been proven to be a suppressor in breast cancer and CCN6 protein is downregulated in human breast cancer tissues." (PMID 37608493, 2023). "The CCN6 gene is lost in some advanced breast cancer while CCN6 knockout mice develop breast cancer." (PMID 38264570, 2023). "In this study, we found for the first time that the breast cancer suppressor CCN6 was degraded through the UPS." (PMID 37608493, 2023). "Our finding that the protein levels of OTUB1 and CCN6 are reduced in aggressive breast cancer suggests that the protein levels of OTUB1 in cancer tissues are more valuable for the prognosis of breast cancer." (PMID 37608493, 2023). "In aggregate, these results show that OTUB1 inhibits the aggressive phenotypes, including migration, proliferation and viability, of breast cancer cells by upregulating CCN6 protein abundance." (PMID 37608493, 2023). "CCN6 is a matricellular protein that critically regulates the tumourigenesis and progression of breast cancer." (PMID 37608493, 2023). "In good agreement with previous reports, we found that CCN6 was downregulated in breast cancer tissues." (PMID 37608493, 2023). "In this study, we identified OTUB1 as a new regulator of breast cancer by stabilizing the tumour suppressor CCN6." (PMID 37608493, 2023). "This study aims to investigate the regulation of CCN6 by ubiquitination and deubiquitinating enzymes (DUBs) in breast cancer." (PMID 37608493, 2023). "Together, our results reveal a novel and critical role of OTUB1 in regulating CCN6 stability and breast cancer." (PMID 37608493, 2023). "Overexpression of CCN6 protein in aggressive breast cancer cells with low endogenous CCN6 abundance diminished their aggressive phenotypes, indicating that increasing the protein expression of CCN6 is favourable for breast cancer treatment." (PMID 37608493, 2023).
breast carcinoma (continued). "In this study, we found that OTUB1 inhibited the aggressive phenotypes of breast cancer by stabilizing CCN6, a specific and potent suppressor in breast cancer." (PMID 37608493, 2023). "On the basis of these reports, CCN6 has been considered a suppressor of breast cancer invasion and metastasis." (PMID 37590989, 2023). "Deletion of OTUB1, concomitant with reduced CCN6 abundance, increased the migration, proliferation and viability of breast cancer cells." (PMID 37608493, 2023). "Taken together, these findings demonstrate that OTUB1 suppresses the growth of breast cancer in vivo by increasing the protein levels of CCN6." (PMID 37608493, 2023). "The correlation of OTUB1 and CCN6 in human breast cancer was determined by immunohistochemistry and Western blot." (PMID 37608493, 2023). "The authors showed OTUB1 knockout increases the proliferation and migration of 4T1 mouse breast cancer cells, which can be counteracted by CCN6 expression." (PMID 38264570, 2023). "Blocking new protein synthesis with cycloheximide strongly reduced CCN6 protein levels in 4T1 mouse breast cancer cells, indicating that CCN6 protein levels are tightly regulated by protein degradation." (PMID 37608493, 2023). "Consistently, CCN6 expression is downregulated in human breast cancer; for a review of CCN6 role in breast cancer see." (PMID 34228239, 2021). "While the expression of CCN proteins varies in different cancer types, CCN1, CCN2, CCN3 and CCN4 participate in tumor development and act as oncogenes, but CCN1, CCN3, CCN5, and CCN6 inhibit tumor growth and play tumor-suppressive roles in breast carcinomas." (PMID 34940056, 2021). "In contrast with the prometastatic role of CCN1 and CCN2, CCN6 acts as an oncosuppressor in breast cancer, preserving epithelial differentiation." (PMID 34228239, 2021). "Exogenous CCN6 or small interfering RNA molecules treatment can reduce the effect of CCN6 inhibition, making it a modulator of breast cancer invasion and metastasis." (PMID 34940056, 2021). "Knockdown of CCN6 in breast cancer cells upregulates Snail and ZEB1 expression at the RNA and protein level by activating the IGF1 receptor signaling pathway." (PMID 31514467, 2019). "In the present study we discovered that ectopic CCN6 overexpression in triple negative (TN) breast cancer cells and in cells derived from patients is sufficient to induce a mesenchymal to epithelial transition (MET) and to reduce TICs." (PMID 26933820, 2016). "This study reveals that the matricellular CCN6 protein modulates breast cancer cell plasticity and points to a new mechanism by which CCN6 regulates the transition between epithelial and mesenchymal states and breast cancer initiating cells." (PMID 26933820, 2016). "Extending these observations to human breast cancer, CCN6 overexpression decreased sphere numbers and reduced the ALDH1+ populations in primary cancer cells derived from a patient with TN invasive carcinoma." (PMID 26933820, 2016). "To investigate the role of CCN6 in breast cancer plasticity, we employed MDA-MB-231 and MDA-MB-436 cells." (PMID 26933820, 2016). "Collectively, these data show that ectopic CCN6 overexpression in breast cancer cells is sufficient to reduce breast TICs, and that overexpression of CCN6 in the TIC population reduces their tumorigenic and metastatic abilities in vivo." (PMID 26933820, 2016). "CCN6 overexpression in breast cancer cells resulted in Slug downregulation and MET, which was completely reversed upon Slug overexpression, indicating a central role for Slug in this process." (PMID 26933820, 2016). "CCN6 exerts breast cancer growth and invasion inhibitory functions, but the mechanisms remain to be defined." (PMID 26933820, 2016). "We present evidence that CCN6 suppresses breast cancer initiation by inhibiting Slug-dependent EMT and TIC programs." (PMID 26933820, 2016). "Breast carcinomas with reduced CCN6 expression have aggressive clinical behavior and frequent metastasis." (PMID 26933820, 2016).
breast carcinoma (continued). "Data presented here show that CCN6 overexpression reduced the number TICs in TN breast cancer cells." (PMID 26933820, 2016). "Our results enable us to pinpoint one novel mechanism by which CCN6 regulates breast cancer cell plasticity implicating a new Slug/Notch1 signaling axis." (PMID 26933820, 2016). "To assess the relevance of our in vitro and animal studies to human breast cancer, we simultaneously investigated the expression of CCN6 and NICD1 proteins in 82 primary invasive carcinoma tissue samples arrayed in a tissue microarray." (PMID 26933820, 2016). "The relevance of these data to human breast cancer is highlighted by the finding that CCN6 protein levels are inversely correlated with Notch1 intracellular activated form (NICD1) in 69.5% of invasive breast carcinomas." (PMID 26933820, 2016). "It has been proposed that CCN6 (WISP3) can suppress EMT in breast cancer cells by inhibiting Zeb1 through the modulation of IGF-1 signaling." (PMID 25852822, 2015). "CCN6-rich medium induces a decrease in IGF-1-stimulated IGF-1R phosphorylation in breast cancer cells, and then results in an inhibition of cellular proliferation." (PMID 16457688, 2005). "We have previously reported that CCN6 is lost in the majority of inflammatory breast cancers, a highly aggressive and metastatic form of breast cancer." (PMID 16457688, 2005). "Restoration of CCN6 expression in inflammatory breast cancer cells results in growth inhibition in vitro and in vivo." (PMID 16457688, 2005). "In this study we characterize the function of CCN6, a recently identified gene that is lost in inflammatory breast cancer, the most lethal form of breast cancer." (PMID 16457688, 2005). "CCN6 is a secreted protein lost in 80% of the aggressive inflammatory breast cancers, and can decrease mammary tumor growth in vitro and in vivo." (PMID 16457688, 2005). "The matricellular protein CCN6 has emerged as a key suppressor in breast cancer." (PMID 37608493, 2023). "Supplementation of CCN6 abolished the effect of OTUB1 deletion on breast cancer." (PMID 37608493, 2023). "Considering that CCN6 is a secreted protein, it may serve as a valuable biomarker in the non‐invasive diagnosis and prognosis of breast cancer." (PMID 37608493, 2023). "CCN6 inhibits both the proliferation and metastasis of breast cancer cells." (PMID 38264570, 2023). "Importantly, OTUB1 expression was downregulated in human breast cancer and positively correlated with CCN6 levels." (PMID 37608493, 2023). "Previous studies have found that CCN6 expression is reduced in aggressive breast cancer." (PMID 37608493, 2023). "In addition, OTUB1 suppressed the aggressive phenotypes of breast cancer both in vitro and in vivo by elevating CCN6 levels." (PMID 37608493, 2023). "In addition, we identified OTUB1 as a bona fide DUB for CCN6, and OTUB1 played a key role in breast cancer by regulating CCN6 protein levels." (PMID 37608493, 2023). "This study identified OTUB1 as a novel regulator of CCN6 in breast cancer." (PMID 37608493, 2023). "Importantly, mice with mammary epithelial cell‐specific deletion of CCN6 developed invasive mammary carcinomas resembling human metaplastic breast cancer, providing a direct evidence that CCN6 is a tumour suppressor for breast cancer." (PMID 37608493, 2023). "Moreover, CCN6 expression is markedly reduced in aggressive breast cancer types, including metaplastic carcinomas and inflammatory breast cancer." (PMID 37608493, 2023). "However, more than a decade of laboratory research has shown that CCN6 plays an inhibitory role in the growth, metastasis, and invasion in breast cancer." (PMID 34940056, 2021). "CCN1, CCN3, CCN5 and CCN6 may play dual roles; their expression can inhibit breast cancer growth, and their absence can induce carcinoma." (PMID 34940056, 2021). "CCN1, CCN3, CCN5, CCN6 play a critical role in survival in breast cancer." (PMID 34940056, 2021).
breast carcinoma (continued). "CCN6 diminishes the IGF-1R signaling pathway to reduce or pause the invasion of breast cancer." (PMID 34940056, 2021). "CCN6 plays a crucial role in tumor suppression in certain cancers, including breast cancer." (PMID 34940056, 2021). "In breast cancer cell lines, CCN6 overexpression inhibits cell growth and invasiveness, while CCN6 induces a epithelial to mesenchymal transition (EMT) and reduces tumor-initiating cells (TIC), which is mediated by the downregulation of Slug and inhibition of the Notch1 signaling pathway." (PMID 30237403, 2018). "Our data pinpoint CCN6 as a novel regulator of Slug in breast cancer progression." (PMID 26933820, 2016). "In view of our results and based on the profound effects of CCN6 overexpression on tumorigenesis and metastasis, we propose that modulation of CCN6 levels may be a potential strategy to prevent or halt breast cancer development." (PMID 26933820, 2016). "Our laboratory has reported that CCN6 is a secreted protein expressed in normal breast epithelium and is reduced or lost in 60% of invasive breast carcinomas and in 79% of inflammatory breast cancers, the most lethal form of locally advanced breast cancer." (PMID 26933820, 2016). "While our studies have demonstrated that CCN6 exerts tumor suppressor functions in breast cancer, CCN6 may promote tumorigenesis in other organs." (PMID 26933820, 2016). "However, CCN6 was shown to be downregulated in invasive and metastatic breast cancers, suggesting that it also exerts a tumor suppressive function." (PMID 26395334, 2015). "The role of CCN6 in breast cancer metastasis has been proved." (PMID 24551846, 2014). "In contrast, studies on CCN6 indicated that it inhibited breast cancer metastasis." (PMID 24551846, 2014). "However, the role of CCN6 in bone metastatic breast cancer remains poorly understood and further studies are necessary." (PMID 24551846, 2014). "The mechanism of CCN6-inhibited breast cancer progression was shown to be mediated by the BMP4/TAK1/p38 pathway, which could induce epithelial-mesenchymal transition, cell invasion, and metastasis." (PMID 24551846, 2014). "Besides, ablation of OTUB1 significantly increased the proliferation and viability of 4T1 cells, while overexpression of CCN6 in OTUB1−/− cells reversed the effect, suggesting that OTUB1 inhibits breast cancer proliferation and viability by elevating CCN6 levels." (PMID 37608493, 2023). "Moreover, CCN6 was shown to inhibit invasion and metastasis of breast cancer in vivo." (PMID 24551846, 2014). "In human breast cancer samples, OTUB1 expression levels were positively correlated with that of CCN6." (PMID 37608493, 2023). "To study the impact of OTUB1 on breast cancer in vivo, we established the mouse allograft model by subcutaneously injecting control, OTUB1−/− and OTUB1−/− + CCN6 (OTUB1−/− cells transfected with CCN6‐overexpressing plasmids) 4T1 cells in nude mice." (PMID 37608493, 2023). "Given that CCN6 acts as a suppressor of breast cancer and its protein stability is enhanced by OTUB1, we investigated the impact of OTUB1 on breast cancer cells in vitro." (PMID 37608493, 2023). "CCN6/WISP-3, on the other hand, has been shown to work as a tumor suppressor blocking breast cancer development." (PMID 34063397, 2021). "We have delineated a molecular pathway through which CCN6 regulates EMT-MET transitions and TICs in breast cancer." (PMID 26933820, 2016). "Collectively, these experiments show that CCN6 overexpression promotes an MET and reduces the ability of breast cancer cells to move and invade." (PMID 26933820, 2016). "We have identified that CCN6 overexpression leads to MET and reduces TICs in aggressive mesenchymal-like breast cancer cells." (PMID 26933820, 2016). "Functionally, deletion of the TSP1 domain (ΔTSP1) abrogated the ability of CCN6 to reduce Notch transcriptional activity, cell invasion, the number of ALDH1+ cells, and the number of tumorspheres formed by MDA-MB-231 and -436 breast cancer cells." (PMID 26933820, 2016).